CRP (C-reactive protein)
Diseases named in the same sentence as CRP in open-access papers (continued):
Sharing a sentence is not in itself a finding about the gene and the disease.
COVID-19 (continued). "Specifically, C-reactive protein (CRP) was elevated in 22.7% of cases, interleukin-6 (IL-6) in 13.6%, and ferritin in 18.2%, consistent with the hyperinflammatory response seen in COVID-19-related cytokine storms." (PMID 40091918, 2025). "The oral administration of enteral formulas has been reported to reduce the pro-inflammatory cytokine IL-6 and C-reactive protein levels in patients with severe COVID-19." (PMID 40002722, 2025). "During acute COVID-19, CD25 levels were positively associated with several serum inflammation markers, including C-reactive protein (CRP), IL-1β, IL-6, IL-10, and tumor necrosis factor (TNF)." (PMID 41310351, 2025). "In a prospective one-year-long observational study including 91 critically ill COVID-19 patients, the C-reactive protein and fibrinogen were shown as independent predictors of mortality." (PMID 40566540, 2025). "This is similar to a previous study in patients with ARDS from COVID-19, which demonstrated a correlation of 0.46 between IL-6 and CRP." (PMID 39969178, 2025). "Inflammatory markers: C-reactive protein and ESR, markers of systemic inflammation, were present at extremely high levels in most cases (mean CRP 92.09 mg/L and mean ESR 58.47 mm/h), indicating an exaggerated inflammatory response associated with COVID-19." (PMID 40141715, 2025). "CRP is known to be involved in the pathogenesis of COVID-19 and, for example, has been demonstrated to correlate with lung lesion appearance and with the severity of the disease, as well as potentially predicting the poor outcome of COVID-19." (PMID 40428859, 2025). "When the population was divided according to COVID-19 disease history, CRP and FGIR were significantly higher in the overweight–obese group in both subgroups." (PMID 40136618, 2025). "CRP is a frequently used acute-phase reactant and was among the earliest biomarkers reported to be elevated in severe COVID-19." (PMID 41373577, 2025). "A study indicated that the inflammatory profile (CRP, IL-10, IL-17, IL-6, TNFα, and IL-1β) observed during the acute phase of severe COVID-19 predicts future long COVID symptoms." (PMID 40048451, 2025). "In non-COVID-19 patients, ferritin correlated with inflammatory markers (CRP, IL-6), fibrinogen, and liver enzymes (AST, ALT, GGT)." (PMID 40364223, 2025). "Biochemical and hematological parameters, such as neutrophil count, lymphocyte count, neutrophil/lymphocyte ratio, CRP, interleukin-6, D-dimer, troponin-I, ferritin, and creatine kinase, were investigated as prognostic indicators for individuals with COVID-19." (PMID 40142738, 2025). "Our study has established a predictive model for COVID-19 severity based on age, cough, sore throat, CRP, WBC, LY, EO demonstrating high accuracy in identifying high-risk patients and effectively guiding personalized treatment decisions." (PMID 40861215, 2025). "This includes proinflammatory markers, such as CRP, procalcitonin and interleukin-6, highlighting the important role of systemic inflammation in COVID-19 progression." (PMID 40283188, 2025). "In 2021, individuals with moderate to severe COVID-19 experienced elevated levels of CRP and NLR compared to those with mild COVID-19, just like during the first wave of the disease." (PMID 40284924, 2025). "The significance of CRP in acute inflammation is well established, particularly in conditions such as COVID-19 and community-acquired pneumonia (CAP), where elevated CRP levels correlate with disease severity and outcomes." (PMID 40282303, 2025). "Outcomes immune/inflammatory markers: In COVID-19, lymphocytes are often reduced (indicating low immune response), while enhanced inflammatory markers such as C-reactive protein (CRP) and cytokine IL-6 are significant predictors of severe or Long COVID." (PMID 40910061, 2025). "Children with influenza A in 2024 and 2015–2016 had higher rates of CRP > 1 mg/dL (both > 50%) compared to influenza B in 2015–2016 or COVID-19 (≤32.5%, p < 0.043)." (PMID 40142409, 2025).
COVID-19 (continued). "In one study, HFNC was used in the early treatment of patients with severe COVID-19 and significantly improved CRP and NEUT count after 3 days of oxygen administration compared with COT." (PMID 40017621, 2025). "C-reactive protein (CRP) is one of the most consistently elevated markers during acute COVID-19 and remains elevated in patients with post-COVID complications, correlating with ongoing systemic inflammation and the fibrosis risk." (PMID 40872813, 2025). "Severe COVID-19 is characterized by pronounced systemic inflammation, as evidenced by elevated levels of C-reactive protein (CRP), ferritin, pro-inflammatory cytokines, and a high neutrophil-to-lymphocyte ratio." (PMID 41158128, 2025). "Small COVID-19 series and case reports have described rapid falls in IL-6, CRP, and D-dimer after TPE, occasionally accompanied by transient haemodynamic and oxygenation improvement, but these observations are heterogeneous and often uncontrolled." (PMID 41517263, 2025). "Elevated IL-6 and C-reactive protein (CRP) levels have also been found in patients with post-COVID-19 painless thyroiditis, further supporting a cytokine-driven pathophysiology." (PMID 41179091, 2025). "Biomarkers for bacterial sepsis overlap with those used for severe COVID-19, such as leukocyte count, C-reactive protein (CRP), and procalcitonin." (PMID 41195955, 2025). "A different tendency was found in the C-reactive protein level, which significantly decreased at the early stage of COVID-19 in the ICW group (MD = 2.56, 95%CI [1.28,3.83])." (PMID 39946361, 2025). "This is reinforced by higher SOFA and APACHE II scores, as well as adverse biochemical parameters (e.g., high D-dimer, CRP) of the high-PSA group that are attributable to severe COVID-19." (PMID 41244516, 2025). "The analysis of the non-COVID-19 cohort showed several significant correlations: AST was positively associated with troponin I, CRP, IL-6, and D-Dimer; creatinine with IL-6 and platelets; and GFR with GGT, while GFR was negatively correlated with IL-6." (PMID 40364223, 2025). "Sepsis/septic shock patients with COVID-19 had lower C-reactive protein (CRP), procalcitonin, IL-6, basophils, and eosinophils compared to sepsis/septic shock patients of other causes." (PMID 41007672, 2025). "Our laboratory findings revealed that diabetic COVID-19 patients also had high levels of inflammatory biomarkers including CRP, ferritin, and D-dimer, neutrophilic leukocytosis, and lymphopenia, corroborating with studies reported in the literature." (PMID 39902024, 2025). "Monitoring inflammatory variables, such as CRP, offers a level of sensitivity that allows for the accurate assessment of acute inflammatory diseases like COVID-19." (PMID 40362375, 2025). "This study aims to assess the prognostic value of erythrogram indicators and C-reactive protein (CRP) levels in 91 intensive care unit-admitted COVID-19 patients, categorized into survivor patients (discharge group) and non-survivor patients (death group)." (PMID 40362375, 2025). "Laboratory results showed impaired oxygenation and elevated C-reactive protein (CRP), confirming the diagnosis of COVID-19, along with leukocytosis." (PMID 41010377, 2025). "The mean concentration of C-reactive protein (CRP) was significantly higher in the PIMS group compared to either COVID-19 or INFLAM patients." (PMID 39940694, 2025). "COVID-19-positive patients also exhibited significantly higher inflammatory and thrombotic markers, including CRP, white blood cell count, D-dimer, and Troponin I (p < 0.01), as well as elevated NT-proBNP." (PMID 40709202, 2025). "Biochemical measures of stress and inflammation (CRP, D-dimer, and ferritin) also correlated with clinical severity of COVID-19, as well as high neutrophil counts and low lymphocyte counts." (PMID 40763987, 2025). "Creatinine, D-dimer, and CRP were positively correlated with clinical outcome of female COVID-19 and IL-6." (PMID 40868247, 2025).
COVID-19 (continued). "CRP levels were consistently elevated in COVID-19 patients during hospitalization compared to healthy controls." (PMID 40621180, 2025). "Of the 180 cases, 61 (33.88%) were patients with COVID-19 (C-reactive protein [CRP]-positive at the time of admission)." (PMID 40502723, 2025). "A total of 307 serum blood samples were collected from 170 acute COVID-19 patients with CRP serum concentrations higher than 10 mg/dl." (PMID 40335840, 2025). "Although various diagnostic markers, such as elevated levels of procalcitonin (PCT) and abnormal C-reactive protein (CRP), are associated with bacterial infections in COVID-19 patients, their specificity remains limited." (PMID 41270012, 2025). "COVID-19 patients showed significantly higher cfDNA levels (p < 0.01), which correlated with CRP, PCT, LDH, and lactate." (PMID 41413709, 2025). "In a prospective cohort study of 1,837 adults hospitalized with COVID-19, selected blood markers of thromboinflammation (i.e., fibrinogen and D-dimer relative to C-reactive protein) predicted cognitive defects at 6-12 months after infection." (PMID 41402665, 2025). "This includes missing data on the WHO COVID-19 severity scale, CRP levels, anti-interleukin treatment, disease progression, progression to mechanical ventilation, and time to discharge." (PMID 40465794, 2025). "Inflammatory and coagulation biomarkers, including D-dimer, C-reactive protein (CRP), ferritin, interleukin-6 (IL-6), and procalcitonin, are routinely measured in moderate–severe COVID-19 and frequently inform clinical decision-making." (PMID 41463074, 2025). "As we have shown in our work, CRP and procalcitonin were also correlated with disease severity in COVID-19 patients." (PMID 40143286, 2025). "CRP levels were significantly higher in severe COVID-19 patients compared to mild COVID-19 (p < 0.001), moderate COVID-19 (p = 0.015), and influenza patients (p = 0.010)." (PMID 41301713, 2025). "While our findings highlight D-dimers, CRP, and lung involvement as key predictors of poor outcomes in COVID-19-related sepsis, several factors warrant further consideration." (PMID 40284898, 2025). "PDW and CRP (platelet distribution width and C-reactive protein) were shown to be very good prognosis markers for severe pneumonia in COVID-19 in reports from both regions." (PMID 41226352, 2025). "An elevated level of C-reactive protein (CRP) and a higher triglyceride (Tg)-to-High-Density Lipoprotein Cholesterol (HDL) ratio were significantly associated with increased IMT in the COVID-19 group." (PMID 41012624, 2025). "Nearly all COVID-19 patients exhibit elevated inflammatory markers, including IL-6, hs-CRP, SAA, and PCT, exceeding normal reference ranges (IL-6: 0-7 pg/mL, hs-CRP: 0-3 mg/L, SAA: 0-6.4 mg/L, PCT: 0-0.046 ng/mL)." (PMID 40046064, 2025). "EAT thickness or volume correlates with high-sensitivity C reactive protein (hs CRP) levels in patients with COVID-19, diabetic peripheral arterial disease (PAD), and suspected metabolic syndrome." (PMID 40933307, 2025). "Japanese COVID-19 patients have reduced levels of inflammatory markers (e.g., CRP) and cytokines (e.g., IL-6), as well as decreased activation of the coagulation and fibrinolysis systems compared with patients from other countries." (PMID 40084335, 2025). "AF and COVID-19 share overlapping pathophysiological mechanisms driven by immune-mediated processes, with inflammatory markers such as C-reactive protein (CRP) and interleukin (IL)-6 correlating with disease severity and mortality." (PMID 41462903, 2025). "The CRP response following the Ad26.COV2.S (Janssen COVID-19 Vaccine)vaccine administration is consistent compared with other vaccines, though probably a little stronger due to its adenoviral vector platform." (PMID 40406137, 2025). "Correlations were observed between the Brixia score, symptom duration from onset, and CRP levels, with the sensitivity of radiological lesions as a marker of COVID-19 progression estimated at 61.1% and 68.1%." (PMID 40423360, 2025).
COVID-19 (continued). "Markers of inflammation and tissue damage, such as CRP, IL-6, and novel biomarkers like suPAR and NETs, have provided significant insights into the pathophysiology of COVID-19." (PMID 40094929, 2025). "The present study examines the prognostic value of erythrogram indicators and C-reactive protein (CRP) levels in intensive care unit (ICU) patients affected by COVID-19, emphasizing their role in predicting severe clinical outcomes." (PMID 40362375, 2025). "Demographic variables, smoking status, COVID-19 symptoms, SpO2 levels, and markers of inflammation (D-Dimer, lymphocytes and white blood cells count, CRP) were recorded." (PMID 40857013, 2025). "The ROC analysis demonstrated that neutrophil count, NLR, and CRP potentially can be used when monitoring the severity of ARDS in COVID-19." (PMID 40761632, 2025). "• A nasopharyngeal COVID-19 polymerase chain reaction (PCR) test on presentation.• COVID-19 serology.• A complete blood count and C-reactive protein on presentation, erythrocyte sedimentation rate.• Renal and liver function tests." (PMID 40303414, 2025). "Increased CRP levels and antibiotic treatment were reported in 8 COVID-19 positive patients who developed pneumonia." (PMID 39998062, 2025). "One study reported that 52% of COVID-19 patients exhibited elevated IL-6 levels, while 86% showed increased CRP, reflecting a significant inflammatory state." (PMID 40046064, 2025). "In a retrospective analysis of laboratory data from 1,429 COVID-19 hospitalized patients, impressively elevated values of D-dimer, procalcitonin, and C-reactive protein (CRP) were reported." (PMID 40566540, 2025). "With a half-life of 18–20 h, the C-reactive protein is the most useful marker of acute systemic inflammation, including infections, sepsis, COVID-19, trauma, and myocardial infarction." (PMID 40217761, 2025). "The parameters most affecting mortality in COVID-19 patients are CRP, procalcitonin, troponin, ferritin, aPTT, RDW, and high monocyte levels." (PMID 40143356, 2025). "This includes the results of examinations defining the severity of COVID-19 and complications such as coagulation disorders or bacterial superinfections, such as CRP, PCT, leukocytes, IL-6, and D-dimers." (PMID 40943751, 2025). "Our findings suggest that D-dimers, CRP, and lung involvement on CT are key independent predictors of poor outcomes in COVID-19-related sepsis." (PMID 40284898, 2025). "The mean CRP in the COVID-19–fungal group was 85.7 mg/L, statistically higher than the 71.6 mg/L recorded in the COVID-19-only group (p < 0.001)." (PMID 40299432, 2025). "The hyper-active drivers in severe COVID-19 exhibited strong positive correlations with typical adverse prognosticators, such as increased D-dimer, CRP, LDH, absolute neutrophil count, and specific comorbidities (kidney disease, hypertension)." (PMID 39921901, 2025). "This multicentre study demonstrates that plasma endostatin at ICU admission was independently associated with AKI, RRT need, and 90-day mortality in critically ill COVID-19 patients after adjusting for age, sex, CRP and creatinine." (PMID 40178654, 2025). "Prior analyses have shown that blood biomarkers of coagulation and inflammation (i.e., fibrinogen and D-dimer relative to C-reactive protein) can help predict cognitive defects in patients hospitalized for COVID-19 up to 12 months after infection." (PMID 41402665, 2025). "Augmented CRP is not only an early biomarker of SARS-CoV-2 infection but is also associated with the severity and prognosis of COVID-19." (PMID 39967737, 2025). "There was a significant trend towards that older patients were less effective by adding CHM in negativity time of nucleic acid, the improvement rate of cough, level of NEU, and CRP, probably due to the older age in later stage COVID-19 included in this study." (PMID 39946361, 2025). "With TyG, age, BMI, triglycerides and CRP were the predictors of IR in participants with past COVID-19 status." (PMID 40273152, 2025).